CD4 (CD4 molecule)
Diseases named in the same sentence as CD4 in open-access papers (continued):
Sharing a sentence is not in itself a finding about the gene and the disease.
multiple sclerosis (continued). "Together, our results reveal a previously unknown mechanism by which FTY720 functions in multiple sclerosis, and suggests that targeting TCF-1 signaling in CD4+ T cells could be a potential treatment strategy for multiple sclerosis." (PMID 26714756, 2015). "D. Contrary to our finding an experimental study on healthy human donor using CD4+ T cells and mouse model for multiple sclerosis showed that 1,25(OH)2D3 inhibits human IL-17A and suppresses mouse IL-17A; other studies in mice imply this regulatory effect on Th17 cells by Vit." (PMID 26504859, 2015). "Reduced myelin basic protein-induced CD4+ T-cell autoreactivity in interferon-β-treated multiple sclerosis patients may be mediated by monocyte-derived interleukin-10." (PMID 25738751, 2015). "Interestingly, the natalizumab-induced decrease in CD4/CD8 ratio in multiple sclerosis patients is significantly related to clinical response." (PMID 24655894, 2014). "Interestingly, we found that Shcbp1 plays a role in CD4+ T cells in the context of the autoimmune EAE model of multiple sclerosis." (PMID 25153088, 2014). "CD8+ Tregs are being extensively investigated in multiple sclerosis (MS) and are believed to exert their regulatory effects that could dominate the effects of self-reactive CD4+ T cells in MS." (PMID 23133648, 2012). "By comparing CSF immune cells from multiple sclerosis relapse with those collected during therapeutic very late antigen-4 blockade, researchers identified immune subsets from various lineages, including CNS border-associated macrophages, CD8 and CD4 TRM cells, and tissue-resident NK cells." (PMID 40510352, 2025). "This residual CD4 elevation supports the idea that helper T-cell–driven inflammation may persist longer, potentially contributing to chronic neuroinflammatory states observed in demyelinating diseases like multiple sclerosis." (PMID 41155593, 2025). "Even though CD4+ T lymphocytes might have a significant influence on the peripheral immune processes that lead to multiple sclerosis, it has been known for a long time that CD8+ T lymphocytes are more prevalent than CD4+ T lymphocytes in the brain lesions of MS patients." (PMID 40255388, 2025). "Given that this kinase is also required for the differentiation of naïve CD4+ T cells into Th17 effector cells, Casein Kinase 2 may serve as a therapeutic target for the treatment of inflammatory diseases including multiple sclerosis and inflammatory bowel disease." (PMID 39607284, 2025). "Furthermore, analysis of human diseases characterized by dominant CD4+ T-cell-mediated pathogenesis, such as Lyme disease, celiac disease, and multiple sclerosis, suggests that restrictive immunodominance might contribute similarly to their pathogenesis." (PMID 39661861, 2024). "Vitamin D treatment in multiple sclerosis (MS) patients reduced the proliferation of CD4+ T cells and myelin basic protein specific T cells, decreased the frequency of IL-6 and IL-17 secreting cells, and promoted the development of IL-10 secreting cells and CD4+CD25+ T regulatory cells." (PMID 29849001, 2018). "In the animal model for multiple sclerosis, EAE, the transfer of regulatory IL-10 producing B cells (B10) into Cd19−/− B cell deficient mice reduces EAE severity and reduces autoantigen-specific CD4+ T cell proliferation and pro-inflammatory cytokine production." (PMID 29361022, 2018). "Studies have found an obvious increased expression of Arrb1 in CD4+ T cells from MS patients; Further, mice which lack the Arrb1 gene are presented to be more likely to survive from experimental autoimmune encephalomyelitis, which is a classical mouse model for multiple sclerosis." (PMID 27669210, 2016). "However, the role of TCF-1 in the regulation of human CD4+ T cell effector function and its relevance to multiple sclerosis and treatment response are unknown." (PMID 26714756, 2015).
multiple sclerosis (continued). "Infection with helminths have been associated with increased numbers of circulating CD4+ CD25+ FoxP3+ Tregs and of autoantigen-stimulated PBLs that produce IL-10 and TGF-β, observations that have been associated with an improved clinical course in patients with multiple sclerosis." (PMID 25410903, 2014). "In multiple sclerosis (MS) lesions, CD8 T cells outnumber CD4 T cells, suggesting that they contribute to MS pathology." (PMID 42171609, 2026). "Infiltrated CD4+ T‐cells were observed interacting with MHC II‐expressing astrocytes in pathological conditions such as Parkinson's disease and multiple sclerosis." (PMID 39873321, 2025). "Th1 cells, a subtype of CD4 + T cells, are capable of inducing NPC cell death in a contact‐dependent manner in the pathogenesis of multiple sclerosis." (PMID 41146571, 2025). "Patients with multiple sclerosis exhibit early-onset of thymus involution, since they feature levels of TREC-containing CD4+ and CD8+ T cells which would be equivalent to those found in 30-year old healthy subjects." (PMID 38469297, 2024). "The proportion of CD20dim CD4+ T cells and abundance of CD4+ relative to CD8+ T cells in cerebrospinal fluid correlated positively with age (R = 0.6799, P = 0.0150) and Age-Related Multiple Sclerosis Severity score (R = 0.8087, P = 0.0014), respectively." (PMID 38385000, 2024). "In an autoimmune setting, the rapid, antigen-independent activation and enhanced migratory capacity of CD4+ TIA cells enabled them to infiltrate the CNS and contribute to an earlier disease onset in a model of multiple sclerosis." (PMID 38838013, 2024). "Here authors show that the E3 ubiquitin ligase RNF213 is central to both physiological and pathologic CD4+ T cell differentiation, and finetunes IFN-β responses in multiple sclerosis." (PMID 39013878, 2024). "While CD4+ T cells have been traditionally regarded as pivotal in NMOSD and multiple sclerosis (MS) pathology, recent studies in human patients have demonstrated that CD8+ T cells instead dominate in MS lesions and display an activated cytotoxic phenotype." (PMID 38440735, 2024). "Evidence suggests elevated SLFN12 methylation levels in CD4+ and CD8+ T cells in the peripheral blood of patients with multiple sclerosis, a chronic inflammatory disease of the central nervous system." (PMID 38075038, 2023). "In fact, β1,6-branched N-glycans were shown to be essential regulator of TCR thresholds in CD4+ T cells in both IBD19 and multiple sclerosis." (PMID 37404372, 2023). "Many clinical studies have shown that the immune system—particularly autoimmune T cells such as Th1, Th17, CD4+ T, and CD8+ T cells—plays an important role in multiple sclerosis." (PMID 36768494, 2023). "In HV, this population represents about 10% of CD4+CD25+Foxp3+T cells, and is increased in diseases such as multiple sclerosis." (PMID 36426347, 2022). "Of relevance, both CD4+ and CD8+ T lymphocytes have been reported in demyelinating lesions of multiple sclerosis." (PMID 36113749, 2022). "The transcription factor STAT1 plays a critical role in modulating the differentiation of CD4+ T cells producing IL-17 and GM-CSF, which promote the development of experimental autoimmune encephalomyelitis (EAE), an animal model of multiple sclerosis (MS)." (PMID 35587373, 2022). "In contrast, augmentation of type I IFN (IFN-β) signaling in inflammatory CNS diseases such as multiple sclerosis blocked excess type II IFN (IFN-γ) signaling, CD4 T regulatory cell suppression and leukocyte infiltration." (PMID 36182964, 2022). "Here, we report that CD4+c-Met+ T cells are detected at increased levels in experimental autoimmune encephalomyelitis (EAE), a mouse model of multiple sclerosis (MS)." (PMID 35488271, 2022). "In early multiple sclerosis (MS), an IFN-γhighGM-CSFhighIL-17low CD4+ T-cell subset termed T helper 17.1 (Th17.1) reveals enhanced capacity to infiltrate the central nervous system." (PMID 35693770, 2022).
multiple sclerosis (continued). "Studies in mouse models of multiple sclerosis have found that CBD (10 mg/kg, i.p.)can affect the levels of both H3K4me3 and H3K27me3 at specific genes, such as IL-4, IL-5, and IL-13, in splenic CD4+ T cells." (PMID 33668469, 2021). "The opposite is seen in multiple sclerosis, where the inflammatory infiltrates are mainly composed of CD8+ T-cells and CD20+ B-cells, while CD4+ T-cells are present only in very low numbers." (PMID 33242149, 2021). "Differentially methylated regions in HLA-DRB1 were observed in CD4+ and CD8+ T cells purified from peripheral blood of 94 women with multiple sclerosis and 94 healthy women, and differential gene expression for HLA-DRB1 gene was detected in whole blood." (PMID 34539625, 2021). "In this study,ITGA4 expression was significantly increased in CSFCD4+ T-cells when compared with blood CD4+T-cells (log fold change 1.7; FDR = 6.7 × 10−16 and6.5 × 10−16 in NID controls and multiple sclerosis,respectively)." (PMID 34761221, 2021). "In experimental autoimmune encephalomyelitis (EAE), a classical animal model of multiple sclerosis, BBB-endothelial cells express CCL2, CCL19, and CCL21, which mediate firm arrest of CCR2+ monocytes and DC as well as CCR7+ CD4 T cells." (PMID 32655545, 2020). "In a murine model of multiple sclerosis (experimental autoimmune encephalomyelitis, EAE), ACE inhibitors suppressed Th17 cells and induction of CD4+FoxP3+ Treg cells, together with activation of the alternative NF-κB2 pathway." (PMID 32987705, 2020). "The α4β1 integrin is important for both CD4 and CD8 T cell migration to the CNS and a monoclonal antibody targeting the α4 subunit provides important benefits for the treatment of persons with multiple sclerosis." (PMID 32655545, 2020). "In mouse models of multiple sclerosis, EAE, ERα signaling suppressed EAE development by increasing PD-1 signaling on cognate CD4+ (Foxp3-) T cells, and that inhibition of PD-1 signaling removed the estrogen dependent inhibition of EAE." (PMID 31849948, 2019). "In order to characterize the PBMC populations that express EZH2, immunophenotyping for EZH2 and flow cytometry analysis was performed in T cells (CD3+, CD4+, and CD8+), B cells, monocytes, and NK cells from 10 multiple sclerosis patients and 13 HC." (PMID 30367633, 2018). "Similar to the mRNA expression findings observed in the whole PBMC population, the percentage of EZH2-positive cells in CD4+ and CD8+ T cells was significantly reduced in untreated multiple sclerosis patients compared to controls." (PMID 30367633, 2018). "An inverse relationship between MAFTRR levels and MAF expression has previously been identified in patients with multiple sclerosis, whereby higher levels of MAFTRR in CD4+ T lymphocyte cells lowers expression of MAF." (PMID 30719032, 2018). "Further, there is a definite trend of increase in memory CD45RO+CD4+ T cells and a decrease in naïve CD45RA+ T cells in the peripheral blood of multiple sclerosis patients." (PMID 29112130, 2017). "The emergence and expansion of autoreactive CD4+ and CD8+ T cells are considered to play a key role in the pathogenesis of multiple sclerosis (MS) and its animal model experimental autoimmune encephalomyelitis." (PMID 28289410, 2017). "Dataset 1 consists of HTS data of sorted CD4 and CD8 T cells, which was part of a phase II trial for poor-prognosis multiple sclerosis." (PMID 26140055, 2015). "Since T cells are major players in multiple sclerosis pathogenesis, we have performed expression analyses of the CIITA-DEXI-CLEC16A-SOCS1 gene cluster in CD4+ and CD8+ T cells isolated from multiple sclerosis patients and healthy controls." (PMID 26203907, 2015). "The shift to CD4+CD25+Foxp3+ Treg and CD4+CD25+Foxp3+CD39+ subset plays a significant role in restricting the detrimental effect of TH17 cells in multiple sclerosis patients." (PMID 22164330, 2011).
multiple sclerosis (continued). "In multiple sclerosis patients, CD8+ T cells outnumber CD4+ T cells in active lesions and the number of CD8+ T cells correlates with the extent of ongoing axon injury and functional disability." (PMID 20814579, 2010). "In CD4 cells, PGJ2 and the TZD ciglitazone reduced IL4 production and in EAE, the animal model of Multiple Sclerosis, PGJ2 blocked splenic T cell production of IL10 and IL4." (PMID 17207275, 2007). "Moreover, in multiple sclerosis, CXCL10 is thought to have a pro-inflammatory impact affecting the Th1 subset of CD4-positive T helper cells, thereby influencing disease evolvement." (PMID 39436967, 2025). "A study involving isolated CD4+ and CD8+ T cells from multiple sclerosis (MS) patients indicated regions of hypermethylation in SLFN12 owing to an overall decrease in SLFN12 expression in whole blood samples of multiple sclerosis patients when compared to controls." (PMID 41303540, 2025). "Their disruptive effect on CD4+ T cell differentiation and the imbalance between T helper cell populations can be most accurately determined using experimental autoimmune encephalomyelitis (EAE) as an animal model of multiple sclerosis (MS)." (PMID 39518908, 2024). "T cell vaccine induces CD4 regulatory T cell response in patients with multiple sclerosis, however, there are currently no reports on CD4 regulatory T cells and NB." (PMID 40625890, 2024). "A more comprehensive understanding of cytokine production by autoreactive CD4+ T cells and cytokine feedback loops active in infiltrating monocytes in EAE could inform future therapeutic discovery efforts in multiple sclerosis." (PMID 37934060, 2023). "p-STAT3 expression in the CD4+ and CD8+ T cells in peripheral blood is higher in patients with active multiple sclerosis than in healthy patients, besides, in several cases of recurrent sclerosis, the p-STAT3 level is closely related to T cell response function." (PMID 33435880, 2021). "CD4+CD28− and activated Th17 cells express cytotoxic molecules, including perforin, granzymes, and adhesion molecules, which enhances their capacity to infiltrate tissues, including brains of patients with multiple sclerosis." (PMID 34440206, 2021). "This is in accordance with previous reports showing no expression of c-Met on naïve T cells, or on circulating CD4+ T cells from multiple sclerosis patients." (PMID 34771724, 2021). "In a multiple sclerosis animal model, hepatocellular IL-7, which was induced by toll-like receptor (TLR) signaling, was described as an important source of IL-7, which enables survival of CD8+ and CD4+ T cells." (PMID 33584648, 2020). "The frequency of CXCR5+ T cells in these lesions is not yet clear; however, in cerebrospinal fluid from multiple sclerosis patients ~20% of memory CD4+ T cells express CXCR5, comparable to the frequency observed in blood." (PMID 30190721, 2018). "In addition to CD4+ cells, large proportion of cells in the infiltrate of diseased BALB/c mice was CD8+, similar with findings in multiple sclerosis." (PMID 28289417, 2017). "Multiple sclerosis (MS) in humans, and its animal model, experimental autoimmune encephalomyelitis (EAE), are characterized by demyelination in the central nervous system (CNS), as a result of inappropriate inflammation and infiltration of CD4+ T cells." (PMID 28400721, 2017). "In vivo, we observed de novo formation, as well as expansion of CD4+CD28null T cells in two different chronic inflammation models, namely the murine CMV (MCMV) model and the experimental autoimmune encephalomyelitis (EAE) model for multiple sclerosis (MS)." (PMID 28386103, 2017). "Daily vitamin D3 supplementation for 3 months in patients with multiple sclerosis did result in an increased proportion of CD4+IL-10+ Tregs, but these were also circulating cells and not site specific." (PMID 24943330, 2014).
multiple sclerosis (continued). "Therefore, conditions that are present and therapeutically relevant in multiple sclerosis and EAE were capable of inducing Shcbp1 expression in CD4+ T cells ex vivo." (PMID 25153088, 2014). "Activated IFNβ–primed CD4+CD45RO+ memory T-cells from multiple sclerosis (MS) patients were not as effective in suppressing NLRP3 inflammasome activation as compared to healthy controls." (PMID 22768094, 2012). "Expression of CCR2, CXCR3 and CCR4 on CD4+ T or CD8+ T cells in blood and cerebrospinal fluid (CSF) for multiple sclerosis (MS) was measured by 3-color flow cytometry, and compared to blood from healthy controls and CSF from patients with other inflammatory neurological diseases (INDs)." (PMID 19662226, 2007). "In a murine model of T‐cell activation, Acthar reduced the activation of CD4+ and CD8+ T cells as well as the production of cytokines (interleukin‐2, interferon γ, and TNFα), which are involved in inflammatory immune responses in autoimmune disorders, such as multiple sclerosis." (PMID 40223398, 2025). "IL-17-producing CD4 T helper (Th17) cells were recognised as a discrete population of CD4+ T cells following the identification of their role in the pathogenesis of experimental autoimmune encephalomyelitis (EAE), a preclinical model of multiple sclerosis (MS)." (PMID 35275333, 2023). "Interestingly, both neutrophil/lymphocyte and platelet/lymphocyte ratios were higher in relapsing patients compared to remitting multiple sclerosis patients and controls while CD3+ T-cells, CD4+ T-cells, CD8+ T-cells and CD19+ B-cells were lower in relapsing patients compared to remitting patients." (PMID 37583699, 2023). "However, the inappropriate expansion of CD4 + C28−T cells was observed in many chronic inflammatory diseases, including autoimmune disorders such as SLE, rheumatoid arthritis and multiple sclerosis, and infectious diseases like infections with cytomegalovirus (CMV)." (PMID 36320075, 2022). "Here,CD4+ T-cells were purified from CSF and blood from 21patients with newly diagnosed treatment-naïve multiple sclerosis and 20individuals with non-inflammatory disorders using fluorescence-activated cellsorting, and their transcriptomes were profiled by RNA sequencing." (PMID 34761221, 2021). "While the expression of CXCR5 may differ between cerebrospinal fluid and tissue, these observations raise the possibility that a large portion of the IL-21+ CD4+ T cells in multiple sclerosis may not express CXCR5." (PMID 30190721, 2018). "Furthermore, CD4 CTL as Eomes-expressing CD4+ T cells are involved in late-onset EAE and may also have a major role in the progressive state of multiple sclerosis in humans." (PMID 28280496, 2017).